INS (insulin)
Diseases named in the same sentence as INS in open-access papers (continued):
Sharing a sentence is not in itself a finding about the gene and the disease.
Hyperinsulinemia (continued). "Athough the mechanisms through which insulin might impair endothelial function are not well clarified, the hyperinsulinemia-induced increase in oxidative stress appears to be involved." (PMID 20334663, 2010). "Furthermore, the combined impact of NEFA and hyperinsulinemia, which is particularly relevant to the insulin resistant metabolic state, has not been explored for its effect on monocyte inflammation." (PMID 21054880, 2010). "We tested whether the impairments in vivo is only translated into myotubes established from subjects with the highest degree of hyperandrogenism or hyperinsulinemia, and subdivided the PCOS group into low/high testosterone or low/high insulin and tested for differences in metabolic phenotype." (PMID 21209881, 2010). "However, although indirect, evidence from previous studies using different modes of insulin and glucose administration does not point to any substantial effects of hyperinsulinemia itself on sleep." (PMID 17326710, 2007). "Conversely, insulin, HbA1c, HOMA-IR, and AIP show very weak or absent correlations (light green to near-white cells), indicating that in prediabetes, irisin’s variation is not tightly linked to hyperinsulinemia, glycemic control, or plasma lipid atherogenicity." (PMID 41596434, 2026). "When insulin is overproduced or not removed promptly, it may manifest as hyperinsulinemia." (PMID 40549205, 2025). "In the present study, we verified the hypothesis that fundamental intrinsic differences exist between isolated and cultured VSMCs from young men and women and that chronic high levels of insulin-mimicking hyperinsulinemia induce remodeling of human VSMCs independent of sex hormones." (PMID 40137469, 2025). "Furthermore, exercise is known to moderate insulin levels and sensitivity, and the pathophysiology of PCOS can be exacerbated by hyperinsulinemia; therefore, regular physical activity may delay or prevent the expression of PCOS in women who are susceptible to it." (PMID 40821310, 2025). "Indeed, peripheral hyperinsulinemia leads to an increase in the insulin level in the brain, because the transport of molecules across the blood–brain barrier (BBB) is highly affected by the variation in their peripheral levels, especially the high level of insulin." (PMID 40943177, 2025). "The euglycemic clamp without hyperinsulinemia is used to keep blood glucose at slightly lower than normoglycemic levels by adjusting the intravenous glucose infusion rate (GIR) when the GIR can reflect the hypoglycemic effect of insulin preparations, i.e., pharmacodynamic characteristics." (PMID 40284414, 2025). "Therefore, the presence of a very high fasting insulinemia (190 mIU/L, RV: 5–25) in contrast to a normal blood C-peptide level (4.5 μg/L on Architect i2000, RV: 0.8–5.2) raised the question of hidden injections of insulin analogs not admitted by the patient (exogenous hyperinsulinemia)." (PMID 39071705, 2024). "Considering the diverse proto-oncogenic roles of the Cbl family and the critical roles of the IRS family in insulin signaling, we speculate that C-CBL may play an important role in mediating IRS protein neddylation, which could have implications for cancer patients with T2DM or hyperinsulinemia." (PMID 38272982, 2024). "However, there is growing support for the theory that hyperinsulinemia may be the first abnormality in the pathogenesis of T2DM, with the main hyperinsulinemic factors being excessive insulin secretion from beta cells and/or decreased hepatic clearance of insulin." (PMID 37189715, 2023). "Moreover, under controlled conditions of comparable plasma amino acid concentrations at either low or high insulin concentrations, the amino acid-induced stimulation of whole-body protein synthesis (in comparison to basal rates) was not augmented further by hyperinsulinemia." (PMID 38201949, 2023).
Hyperinsulinemia (continued). "However, we also found adipose CS to be markedly more pronounced in adipocytes from individuals with T2D, who did not have higher insulin levels than the included group of matched nondiabetic obese individuals, suggesting factors other than hyperinsulinemia in promoting CS in T2D." (PMID 37317964, 2023). "Additionally, the rate of lipolysis in VAT is higher than in subcutaneous adipose tissue, increasing the circulation of nonesterified fatty acids, which may affect hepatic insulin inactivation and contribute to IR and hyperinsulinemia." (PMID 35783191, 2022). "Therefore, while the insulin replacement study suggests that dapagliflozin exerts the majority of its effect through reversing hyperinsulinemia, future studies would be required to rule out potential effects of dapagliflozin on each of these other mediators of tumor growth." (PMID 35595952, 2022). "Moreover, some researchers supposed that high-dose STZ may severely damage the function of pancreatic β-cells and produce a decrease in insulin secretion, which was similar to our findings that the diabetic model may not show obvious hyperinsulinemia." (PMID 36160420, 2022). "However, SNAT1 expression seems to be closely connected to insulin levels and increases could be a consequence of the hyperinsulinemia, and may therefore not be relevant during nutrient deprivation, usually accompanied by hypoinsulinaemia." (PMID 35344549, 2022). "In addition vitamin D deficiency also appears to have an impact on insulin sensitivity in women with PCOS, as assessed by HOMA-IR; however, further assessment of insulin sensitivity by hyperinsulinemia euglycemic clamp in women with PCOS did not confirm this association." (PMID 34684492, 2021). "It has been shown that the EDIH provides better predictions about both fasting and non-fasting C-peptide concentrations rather than dietary insulin index (DII), indicating that the EDIH may be better in evaluating the dietary impacts of hyperinsulinemia on disease risk." (PMID 33985566, 2021). "In this context, we note that insulin in plasma from wildtype mice would be vulnerable to degradation by any IDE released by hemolysis, which would be absent in plasma from IDE-KO mice, which could conceivably account for the apparent hyperinsulinemia in IDE-KO mice." (PMID 33477364, 2021). "In support of this view, non-diabetic obese-insulin resistant subjects can cope with the important metabolic demand by enhanced insulin synthesis and secretion and increased beta-cell mass, thereby preserving normal blood glucose levels at the cost of hyperinsulinemia." (PMID 33652748, 2021). "Furthermore, IR is a pathophysiological condition whereby a normal insulin concentration does not adequately promote a normal insulin response in the peripheral target tissues such as adipose, muscle and liver, which results in hyperinsulinemia." (PMID 34209146, 2021). "In relation to the mechanism of AAPs-induced hyperinsulinemia, D2, D3, 5-HT2A/2C and 5-HT1A receptors expressed in the β-cells might be partially responsible, considering that peripheral dopamine and serotonin generally inhibit insulin secretion in a subtle way." (PMID 33800403, 2021). "Insulin resistance occurs when the effect of insulin on cells, such as fat, muscle, and liver, is lower than normal, resulting in decreased glucose utilization, increased liver gluconeogenesis, and increased blood glucose concentration and compensatory hyperinsulinemia." (PMID 34975540, 2021). "Also NZO mice showed early hyperinsulinemia, impaired glucose tolerance, and insulin secretion could not be stimulated by glucose." (PMID 32374082, 2020). "Clinical data emphasize that the severity of hyperinsulinism is the main factor to determine whether CH develops or not and whether CH is symptomatic or not since the clinical course of CH in general parallels the serum insulin levels." (PMID 31840185, 2020).
Hyperinsulinemia (continued). "As the pEHC is a profound experimental model the exogenous hyperinsulinemia induced during this model in the horses would not necessarily correlate with insulin during laminitis induction, and therefore this study was unable to address this interesting hypothesis." (PMID 31805097, 2019). "Also, studies in GPR40/FFAR1-deficient mice confirmed a role for FFAs in the amplification of insulin secretion; these mice did not develop hyperinsulinemia nor glucose intolerance when given a high-fat diet, since this deficiency protected from the harmful metabolic effects of high-fat feeding." (PMID 29565831, 2018). "Thus, the use of endogenous molecules that increase insulin clearance, without the side effects or adherence concerns, could be a potential treatment for hyperinsulinemia." (PMID 29093479, 2017). "Similarly, ECE protein, which is responsible for cleaving inactive proendothelin to the active endothelin‐1 peptide, was upregulated in response to hyperinsulinemia in LHCs (basal: 0.80 ± 0.06; insulin: 1.08 ± 0.17, P = 0.02); however, no significant changes were detected in T2DM subjects." (PMID 27796268, 2016). "However, the molecular pathways by which chronic stress induces histopathological lesions in the liver in patients with T1DM are not clear because the mechanisms of hyperinsulinemia and hepatic and peripheral resistance to insulin are not usually the predominant mechanisms." (PMID 25789328, 2015). "However, supplementation with TB protected IUGR piglets from hyperinsulinism and maintained normal metabolism of glycose in the liver of IUGR piglets, and the mRNA expression of INSR and Akt2 was downregulated which corresponded to the decreased concentration of insulin." (PMID 26317832, 2015). "Since the origins by which an individual may become hyperinsulinemic are variable, the studies presented here were conducted in cell culture models in which the amount and duration of insulin exposure could be carefully regulated independent of any other physiologic responses to hyperinsulinemia." (PMID 25259572, 2014). "However, also note that simple incubation of hepatocytes of type 2 diabetic humans in the absence of insulin (and/or other factors) can break this vicious cycle, and this suggests that dietary measures that are effective in reversing hyperinsulinemia should be similarly effective." (PMID 26237474, 2014). "Moreover, insulin regulates mitochondrial metabolism and oxidative capacity through PI3K/Akt signaling; therefore, decreased Akt signaling by hyperinsulinemia- mediated IR may have profound effects on mitochondrial function in neurons and result in subsequent increased oxidative stress." (PMID 25215171, 2014). "Since plasma insulin concentrations in the present study were not influenced by leukocyte ACE2 deficiency, then these results suggest that the degree of glucose intolerance in chimeric ACE2-deficient mice was not sufficient to further augment hyperinsulinemia in chronic 4 month HF-fed mice." (PMID 22518292, 2012). "Moreover using the same hyperinsulinemia strategy, that research group also documented reduced PDC activity and muscle lactate levels with increased muscle glycogen stores presumably related to increased muscle carnitine levels following IV infusion of insulin and carnitine." (PMID 19341458, 2009). "Our findings show that CDDO-EA did not affect glucose and insulin levels of mice fed an LFD with CDDO-EA, and HFD feeding alone induces glucose intolerance and hyperinsulinemia." (PMID 40564946, 2025). "Under high-fat diet, L-IDE-KO mice develop compensatory hyperinsulinemia, further supporting a key role for hepatic IDE in maintaining systemic insulin sensitivity through both enzymatic and non-enzymatic mechanisms." (PMID 40724942, 2025). "The compensatory hyperinsulinemia observed in PCOS patients provokes an overstimulation of tissues and organs, such as the ovaries, that do not normally depend on insulin for their function." (PMID 40871560, 2025).
Hyperinsulinemia (continued). "Establishing combined treatment of antidiabetic drugs that do not induce hyperinsulinemia, such as SGLT2-I, and a low-carbohydrate diet that raises less insulin is a crucial matter." (PMID 38304078, 2024). "To explore the additive effect of insulin and JAKi in RA patients, we compared CD4+ cells within the JAKi-treated (seven with hyperinsulinemia) and non-JAKi-treated groups (five with hyperinsulinemia)." (PMID 39768214, 2024). "In addition, there is extensive evidence that chronic hyperinsulinemia (whether created by exogenous insulin infusion or by the stimulation of endogenous insulin) can lead to a specific defect in the insulin-mediated non-oxidative (glycogen synthetic) post-receptor pathway." (PMID 38791525, 2024). "Out of the 139 children analyzed, 95 (68.35%) showed a peak insulin level > 100 uIU/mL during the OGTT, while in 44 cases (31.65%) the suspected hyperinsulinemia was not confirmed." (PMID 38920551, 2024). "Our study also found that non-Hispanic Blacks and Hispanics consistently had higher age-standardized levels of fasting insulin, HOMA-IR index, and greater prevalence of hyperinsulinemia and IR compared to non-Hispanic Whites." (PMID 39606490, 2024). "Comparing patients with and without hyperinsulinemia, we found statistically significant differences in weight, BMI, WC, HC, IGF-1, uric acid, VLDL, triglycerides, and basal insulin levels." (PMID 38920551, 2024). "OLETFs have elevated blood glucose, plasma insulin, and leptin levels, an effect consistent with the OLETF phenotype and in agreement with other findings, though the exact mechanisms behind hyperinsulinemia are not fully clear." (PMID 37298724, 2023). "Non-fasting serum levels of metabolic hormones, leptin, insulin and cortisol, determined in the five affected patients from the SOPP were within the normal range except in one proband that presented hyperinsulinemia." (PMID 37083980, 2023). "Thirdly, due to the lack of recorded insulin concentration data, we were unable to compare serum AP levels with HOMA-IR and the clamp test for hyperinsulinemia." (PMID 37863941, 2023). "Hyperinsulinemia resulted in increased phosphorylation of Akt and mTOR with reduced nonphosphorylation of 4E‐BP1 and LC3B‐II, all p < 0.0005, but this effect of insulin was not altered by administration of BHB." (PMID 35986508, 2022). "Since canagliflozin was shown to inhibit hyperglycemia and hyperinsulinemia without adverse consequences, cotreatment with Akt or PI3K inhibitors that inhibit Akt2 in insulin-responsive tissues should be considered." (PMID 35578699, 2021). "Nonfasting and fasting insulin levels at 8 weeks of HFD were also significantly reduced in TSC2-KOPlacenta mice compared with controls, suggesting lack of hyperinsulinemia development in these animals under HFD treatment." (PMID 34032632, 2021). "Hyperinsulinemia may induce increased albuminuria through its direct effect on glomerular hyperfiltration, endothelial dysfunction, and increased vascular permeability over the long term, although in non-diabetic subjects, even a short-term insulin infusion increases urinary albumin excretion." (PMID 34300354, 2021). "HFD feeding often results in hyperinsulinemia, and BS1 covers a cis-acting element (between −1347 and −1353) reported to mediate the negative effects of insulin on Slc27a1 gene transcription in adipocytes." (PMID 32059412, 2020). "Although plasma insulin levels were significantly decreased in CDAHFD-fed KK-Ay mice, this dietary regime did not affect hyperinsulinemia in ob/ob mice." (PMID 31023717, 2019). "Extraordinarily, a valuable reduction of fasting circulating amino acids usually increased in hyperinsulinemia, but without any changes in HOMAR or circulating insulin, was observed." (PMID 31121885, 2019). "Since the fasting plasma insulin (FPI) concentration did not change and was, in fact, slightly reduced, hyperinsulinemia cannot explain the reduction in basal HGP." (PMID 31470605, 2019).
Hyperinsulinemia (continued). "A difference in glucose clearance and hyperinsulinemia was demonstrated in Mrap2−/− mice on a C57/BL6N background, while on a 129/Sv genetic background no changes in insulin and glucose handling were found." (PMID 30352741, 2018). "Thus, the inhibition of glucose‐induced insulin release by cervical VNS was highly consistent in our mixed population of rats suggesting that VNS impairs glucose tolerance in subjects with (e.g., congenic LH rats) and without (e.g., LN or LL rats) hyperinsulinemia or other metabolic risk factors." (PMID 30569658, 2018). "Increased insulin levels are found in both obese and lean patients treated with VPA, suggesting that hyperinsulinemia is not a consequence of increased weight but probably a direct effect of VPA treatment." (PMID 28694790, 2017). "By contrast, lean mice do not display hyperinsulinemia, and we believe that the increase in IDE expression and insulin clearance, in these mice, are important for the effectiveness and safety of physical exercise." (PMID 27467214, 2016). "While fasting glucose level was not obviously different between these two groups, fasting insulin level was significantly increased in HFD group, indicating that hyperinsulinemia had been attained in tga20 mice after 4 weeks of treatment." (PMID 26658276, 2015). "In contrast, hyperinsulinemia did not develop until week 12 in the HFD mice; at this time point, the circulating insulin in the HFD group was 72% higher than that in the control group." (PMID 26023930, 2015). "In contrast, B6 mice have lower basal levels of insulin compared with CBA mice and did not develop hyperinsulinemia nor glucose intolerance on increased body fat mass, in response to the 3w of SRD." (PMID 26085100, 2015). "Both exenatide and 0.081% evogliptin alone did not significantly improve hyperinsulinemia in HF-DIO mice (P = 0.535 and P = 0.071 by One-way ANOVA, respectively), which corroborated the results of the insulin tolerance test." (PMID 26633898, 2015). "Although hyperinsulinemia triggers the hepatic lipogenesis, CLA-induced hepatic steatosis in the absence of insulin suggests the involvement of other regulatory mechanisms affecting hepatic lipid accumulation." (PMID 21869929, 2012). "Akt expression was not affected by DEX treatment, even with hyperinsulinemia and upregulated INSR, indicating the unaltered insulin signaling cascade." (PMID 22623960, 2012). "Third, the assessment of hyperinsulinemia using a single step infusion design may not reveal differences in splanchnic palmitate and VLDL-TG kinetics at different insulin infusion rates." (PMID 38901559, 2024). "Additionally, the LPHF-F2 group showed lower glucose intolerance and hyperinsulinemia than the NPHF-F2 group, insulin sensitivity was not altered, and the islet area was lower." (PMID 36704794, 2022). "The results showed that insulin decreased the membranous expression of GLUT4 but did not alter its total expression both in BV2 cells and primary microglia, suggesting hyperinsulinemia impaired GLUT4 membrane translocation in microglia." (PMID 36466168, 2022). "Several correlations between OGIS index, AUCg, and plasma insulin OGTT were found in both tRES-HESP treatment and placebo periods, as expected for the inverse relationship of insulin sensitivity to dysglycemia and hyperinsulinemia in subjects independent of treatment." (PMID 34371884, 2021). "Since insulin can activate the PI3K/AKT/mTOR pathway, it is predicted that hyperinsulinemia, in the absence of other metabolic dysfunctions, may drive the aggressive biology of TNBCs in insulin-resistant women." (PMID 31315653, 2019). "Likewise, maternal HFD did not alter insulin tolerance in any genotype, despite hyperinsulinemia in KO from HFD-fed dams, indicating that maternal HFD does induce insulin intolerance in the peripheral organs involved in glucose clearance." (PMID 28743985, 2017).